LOX (lysyl oxidase)
Diseases named in the same sentence as LOX in open-access papers (continued):
Sharing a sentence is not in itself a finding about the gene and the disease.
exfoliation syndrome (1 paper, 2025). An autosomal dominant disorder caused by mutations in the LOXL1 gene, encoding lysyl oxidase homolog 1. "LOXL3 is of special interest given that LOXL1, a related lysyl oxidase, is the well-known genetic risk factor for exfoliation syndrome and XFG, with a single polymorphism accounting for the majority of cases." (PMID 41042282, 2025).
follicular lymphoma (1 paper, 2022). Follicular lymphoma is a form of non-Hodgkin lymphoma characterized by a proliferation of B cells whose nodular structure of follicular architecture is preserved. "The enzyme lysyl oxidase (LOX) is involved in the rise of collagen cross-linking in Hodgkin lymphomas, while altered architecture, shown by scanning electron microscopy and polarized light microscopy is involved in advanced follicular lymphomas." (PMID 35008423, 2022).
Glucose intolerance (1 paper, 2022). Glucose intolerance (GI) can be defined as dysglycemia that comprises both prediabetes and diabetes. "Furthermore, overexpressing HIF1α induces AT dysfunction, which is reflected by systemic glucose intolerance and an increased immune cell filtration and enhanced fibrosis of AT primarily through up-regulating lysyl oxidase (LOX)." (PMID 35211733, 2022).
Granuloma (1 paper, 2020). A compact, organized collection of mature mononuclear phagocytes, which may be but is not necessarily accompanied by accessory features such as necrosis. "In smokers with granuloma due to AP, the products of lipid peroxidation, as 8-iso-PGF(2a) and products of the LOX-pathway, were increased at the expense of cyclooxygenase products." (PMID 33138302, 2020).
Hepatitis (1 paper, 2025). Inflammation of the liver. "Inflammation-driven conditions such as hepatitis not only foster fibrosis but also contribute to carcinogenic mutations, with LOX sustaining a pro-inflammatory and ECM rigidifying niche, thereby perpetuating an “inflammation-fibrosis-cancer” continuum." (PMID 40661776, 2025).
idiopathic scoliosis (1 paper, 2011). A scoliosis with no known cause. "This study was designed to test for association between common polymorphisms in the five human lysyl oxidase genes with the phenotype of adolescent idiopathic scoliosis." (PMID 21740577, 2011). "Despite suggestive evidence in model organisms, common variants and known coding SNPs in the five human lysyl oxidase genes do not confer increased genotypic risk for adolescent idiopathic scoliosis." (PMID 21740577, 2011).
intrahepatic cholangiocarcinoma (1 paper, 2024). A carcinoma that arises from the intrahepatic bile duct epithelium in any site of the intrahepatic biliary tree. "Spontaneous and orthotopic murine models of intrahepatic cholangiocarcinoma upregulate all 5 lysyl oxidase isoforms." (PMID 39101793, 2024).
invasive carcinoma (1 paper, 2016). A carcinoma that is not confined to the epithelium, and has spread to the surrounding stroma. "There is some controversy concerning the biological relevance of LOX to the molecular pathogenesis of invasive carcinomas." (PMID 26882568, 2016).
keloid (1 paper, 2021). An irregularly shaped, elevated mark on the skin caused by deposits of excessive amounts of collagen during wound healing. "In addition to collagen-degrading enzymes, we examined the gene-expression levels of collagen-cross-linking enzymes, such as LOX, LOXL-1, LOXL-2 and LOXL-3, finding that they were substantially upregulated in keloid dermal fibroblasts relative to either normal or hypertrophic dermal fibroblasts." (PMID 33672186, 2021).
kidney cancer (1 paper, 2010). Primary or metastatic malignant neoplasm involving the kidney. "The 26 down-regulated microRNA had 170 direct up-regulated mRNA targets, including oncogenes VEGFA, LOX, LOXL2 and FAS, well known to be involved in kidney cancer." (PMID 20420713, 2010).
Lewis lung carcinoma (1 paper, 2025). "ATP7A depletion reduces lysyl oxidase (LOX) activity, which in turn limits the metastasis in murine models of Lewis lung carcinoma cells." (PMID 40002764, 2025).
liver disease (1 paper, 2025). "Lysyl oxidase (LOX) is another significant metabolic modulator implicated in liver disease." (PMID 40867622, 2025).
liver neoplasm (1 paper, 2022). Tumors or cancers of the LIVER. "As LOX and LOXL3 were both found to be overexpressed in LC and associated with worse OS, further exploration of potential interacting drugs was conducted by using Coremine Medical, which identified 30 drugs that were associated with both LOX and LOXL3 in liver neoplasms." (PMID 35311155, 2022).
lymphatic disease (1 paper, 2011). "In the future, the combination of molecular markers with proven predictive value for lymphatic disease like ECAD, podoplanin, p16, bmi-1, LOX and histopathological features could allow an individual risk stratification with possible impact on treatment strategy." (PMID 21639893, 2011).
metastatic melanoma (1 paper, 2011). A melanoma that has spread from its primary site to another anatomic site. "The Oncomine also showed co-expression of CHL1 with another known cancer metastasis-associated gene, lysyl oxidase (LOX) in metastatic melanoma." (PMID 21408220, 2011).
mitral valve prolapse (1 paper, 2014). A fairly common and often benign valvular heart disorder characterized by redundancy or hooding of mitral valve leaflets so that they prolapse into the left atrium, often causing mitral regurgitation. "Dudakova and Jirsova hypothesized that very similar changes in the extracellular matrix, particularly at the level of collagen metabolism, including lysyl oxidase (LOX) impairment in mitral leaflets, may reflect an association between KC and mitral valve prolapse." (PMID 24864193, 2014).
mucinous ovarian cancer (1 paper, 2018). An invasive malignant neoplasm that arises from the ovary and is characterized by the presence of malignant epithelial cells that contain intracytoplasmic mucin and may resemble the epithelial cells of the endocervix or gastrointestinal tract. "The immunohistochemical analysis of LOX, COL1A2, COL3A1, COL21A1, and ALDH1A1 was performed for few cases of endometrioid, serous, and mucinous ovarian cancer in order to verify the localization of analyzed proteins in the real cancer tissue." (PMID 30583585, 2018).
Multiple Myeloma (1 paper, 2025). "Consistent with this, we observed significantly higher expression levels of ATP7A and LOX in extramedullary multiple myeloma (EMM) patients compared to bone-marrow-confined MM patients in our previous transcriptomic analysis." (PMID 40002764, 2025).
myopia (1 paper, 2021). "These collective findings indicate that modulation of the gene expressions of regulators of ECM metabolism, such as HIF 2A, LOX, MMPs, and TIMPs, and several ER stress factors may be involved in the pathogenesis of myopia." (PMID 34698138, 2021). "As of this writing, only HIF 1A has been reported to be involved in the pathogenesis of myopia, and thus, this represents the first demonstration of the ALs-related alteration of the HIF 2A and LOX signaling." (PMID 34698138, 2021).
neuropathy (1 paper, 2014). A disorder affecting the nervous system that manifests with pain, tingling, numbness, and/or muscle weakness. "In addition, our results confirm previous findings that HFD-fed C57BL/6 mice develop prediabetes and neuropathy, and this may be associated with changes in LOX and VEGF, as indicated by the strong correlations with the mean dendrite length." (PMID 25404943, 2014).
ovarian endometriosis (1 paper, 2021). A non-neoplastic disorder characterized by the growth of endometrial tissue in the ovaries. "Thus, we speculate that the inhibition of LOX and PTX3 could provide a better treatment for ovarian endometriosis." (PMID 34202354, 2021).
ovarian tumor (1 paper, 2013). "We demonstrate that LOX expression correlates with HIF-1α in 61 cases ovarian tumor tissues and that hypoxia upregulates LOX and HIF-1α expression and migration/invasion of HO8910/HO8910-PM cells via HIF-1α and HIF-2α." (PMID 23545606, 2013). "Such activation of AKT pathway by LOX is consistent with recently published results, which have shown that LOX modulates ovarian tumor progression by stimulating MMPs/FAK/AKT signaling." (PMID 23545606, 2013).
papillary thyroid cancer (1 paper, 2022). "According to the ROC results, TIMP1, LOX, CD276, IFNA1, TLR2, and POSTN were considered to play a more critical role in malignant papillary thyroid cancer or immature cancer of papillary thyroid cancer." (PMID 36120433, 2022). "TIMP1, LOX, CD276, IFNA1, TLR2, and POSTN have different expressions in PTCs, which lead to the various clinical courses of a woman older than 55 years old with papillary thyroid cancer." (PMID 36120433, 2022).
papilloma (1 paper, 2022). A benign epithelial neoplasm that projects above the surrounding epithelial surface and consists of villous or arborescent outgrowths of fibrovascular stroma. "The immunofluorescence staining of mouse tumor tissues revealed prominent LOX signals in Itga11−/− papillomas, whereas there were clearly fewer in Itga11+/+ papillomas." (PMID 36003785, 2022). "The LOX signals were distributed throughout the papilloma stroma and likely represented CAFs, while tumor cells were LOX-negative." (PMID 36003785, 2022).
Paralysis (1 paper, 2018). Paralysis of voluntary muscles means loss of contraction due to interruption of one or more motor pathways from the brain to the muscle fibers. "PB-induced flaccid paralysis also led to twofold reductions in LOX activity levels relative to controls (p < 0.05)." (PMID 30249775, 2018).
periodontitis (1 paper, 2023). An acute or chronic inflammatory process that affects the tissues that surround and support the teeth. "For example, MDA, a by-product of lipid peroxidation and a marker of ferroptosis, has been reported in periodontium from patients with periodontitis and in periodontal tissue, polyunsaturated fatty acids (PUFAs) increase and undergo a series of peroxidation reactions driven by LOX." (PMID 37372983, 2023).
prostate (1 paper, 2011). "LOX has been reported to havetumour suppressor activity and can inhibit proliferation of the prostate cancercell line DU 145 via a mechanism involving interference with FGF2 binding andsignalling cascade." (PMID 21479216, 2011).
pterygium (1 paper, 2021). A wedge-shaped fibrovascular lesion arising from the bulbar conjunctiva and extending to the cornea. "In our case, overexpressed LOXL1 mRNA and protein levels were identified in pterygium, but, in the case of LOX, the messenger remained stable and only the protein levels showed a significant increase in pterygium pathology." (PMID 34945227, 2021). "As compared with LOX, the relative amount of LOXL1 mRNA was correlated with protein expression and showed a significant increase of approximately two-fold in pterygium as compared with healthy conjunctiva (p < 0.001)." (PMID 34945227, 2021). "The protein expression of LOX showed immunostaining that appeared mainly in the ECM and was significantly higher in pterygium." (PMID 34945227, 2021).
pulpitis (1 paper, 2023). Inflammation of the dental pulp. "Amongst the 22 modules, the darkgray module was determined as the most pivotal module for pulpitis, from which 5 core genes, A HMOX1, LOX, ACTG1, STAT3 and GNB5, were selected, and assumed to exert pivotal effects on the pathophysiologic causal links of pulpitis." (PMID 36593446, 2023). "Subsequently, the protein coding genes HMOX1, LOX, ACTG1, STAT3, GNB5 were selected as the core genes, as they were most negatively or positively correlated modules with pulpitis statistically." (PMID 36593446, 2023).
rectal tumor (1 paper, 2021). "Changes in collagen content and alignment during rectal tumor progression as observed in our study could be due to the alterations of lysyl oxidase level in the neoplastic ECM which regulates collagen crosslinking as observed in CRC tissue samples." (PMID 34485136, 2021).
renal failure (1 paper, 2010). "Thus, also a limitation of the present study is that we did not determine the effect of sEH inhibition in animals lacking LOX activity and therefore we cannot provide definite proof for an involvement of LOX in the progression of renal failure after sEH inhibitor treatment." (PMID 20694143, 2010).
renal tumor (1 paper, 2024). "The keydrivers in the stiffening of the renal tumor microenvironment includescollagen IV over collagen I and the LOX enzyme." (PMID 39398183, 2024).
resistant hypertension (1 paper, 2022). "The plasma concentration of LOX was quantified in 34 samples from patients diagnosed with resistant hypertension." (PMID 35885053, 2022).
rheumatic diseases (1 paper, 2021). "Other studies in RA suggested that COX and LOX pathways remain overexpressed and can contribute to subclinical inflammation and relapse of rheumatic diseases." (PMID 34303373, 2021).
schizophrenia (1 paper, 2019). A major psychotic disorder characterized by abnormalities in the perception or expression of reality. "Our analyses placed LOX at the centre of ECM remodelling networks that are associated with BD, schizophrenia and AD, involving Elastin, which is the direct target of LOX, together with TGF-β1 and MMP9." (PMID 31477687, 2019). "Ours is the first study that identifies LOX as an astroglial target of lithium and as a common factor and potential surrogate biomarker in BD, schizophrenia and AD." (PMID 31477687, 2019). "Our analyses identified LOX and PPAR-γ as primary astroglial targets of lithium that are relevant to BD and schizophrenia, whilst flavonoids have potential astrocyte-modifying effects that are relevant to BD and AD." (PMID 31477687, 2019).
scoliosis (1 paper, 2011). A congenital or acquired spinal deformity characterized by lateral curvature of the spine. "The mechanisms by which lysyl oxidase enzymes putatively influence scoliosis in experimental models show effect modification, specifically with copper exposure." (PMID 21740577, 2011).
tendinopathy (1 paper, 2016). "In conclusion, four strong candidate genes (COL11A2; ELN; ITGB3; LOX) were identified as differentially expressed in tendinopathy, functionally linked to features of tendinopathy and implicated in the aetiology of other connective tissue diseases." (PMID 26804977, 2016). "The current study identified four strong candidate genes (COL11A2; ELN; ITGB3; LOX) that are differentially expressed in tendinopathy, functionally linked to features of tendinopathy and previously implicated in the aetiology of other connective tissue diseases." (PMID 26804977, 2016).
Ureteral obstruction (1 paper, 2020). Obstruction of the flow of urine through the ureter. "The involvement of LOX, not only as a target, but as a modulator of YAP1, was reported in unilateral ureteral obstruction, where upregulation of the ERK/YAP1/Kfl5/cyclin D axis was suppressed by LOX inhibition." (PMID 32708046, 2020).
tumor (661 papers, 2001 to 2026). "Evidence related to the LOX protein shows that its expression is significantly associated with invasion depth, tumor differentiation, lymph node metastasis, lymphatic invasion, venous invasion, and peritoneal metastasis." (PMID 40906383, 2025). "In circulating monocytes, LOX-dependent up-regulation of β1 integrin receptor signaling drives its penetration into GBM tissues to obtain tumor-associated macrophage phenotype and promotes GBM survival and angiogenesis by secreting SPP1." (PMID 39206155, 2024). "Pan-LOX inhibition downregulated macrophage invasive signatures in vitro, rendering tumor-associated macrophages more susceptible to chemotherapy." (PMID 39101793, 2024). "Accumulation of thick and long collagen fibers cross-linked by LOX reduces stromal elasticity and forms stiff tumor." (PMID 38546906, 2024). "Several studies have shown that aberrant expression of LOX in solid tumors, including ChSs, is associated with tumor progression and metastasis in virtue of the LOX’s ability to alter the ECM, increasing tumor cell migration and invasion." (PMID 38891109, 2024). "The EWS-FLI oncoprotein in Ewing sarcoma decreases the expression of LOX, and the observed tumor-suppressive effects have been associated with a specific pro-peptide domain." (PMID 39154307, 2024). "CCA upregulates all 5 lysyl oxidase isoforms, and pan-LOX inhibition reverses tumor-induced mechanical forces associated with chemotherapy resistance to improve chemotherapeutic efficacy and reprogram antitumor immune responses." (PMID 39101793, 2024). "Studies have shown that copper chaperone ATOX1 is involved in the ATP7A-LOX pathway associated with tumor metastasis, and the inhibition of ATOX1 expression reduces LOX activity and the rate of cancer cell metastasis." (PMID 38200525, 2024). "In mouse models of breast cancer and lung cancer in situ, deletion of ATP7A inhibited LOX activity, leading to a significant loss of tumor growth and reduction of tumor metastasis." (PMID 38970072, 2024). "This progressive stiffening has been associated with increased lysyl oxidase-mediated collagen crosslinking within the tumor." (PMID 39716322, 2024). "The tumor-associated ECM is characterized by collagen crosslinking catalyzed by lysyl oxidase (LOX)." (PMID 37532712, 2023). "The mouse and cell-culture data strongly suggest a loss of naturally occurring inhibitory activity of the Gln LOX-PP variant compared to wildtype Arg LOX-PP which ultimately results in the elevation of LOX production and tumor development." (PMID 37298359, 2023). "In fact, it has been shown that aberrant LOX expression is implicated in tumor progression and therapy resistance." (PMID 37284199, 2023). "From the TCGA and the GEO database analysis, LOX was significantly associated with the level of macrophage infiltration, which is commonly referred to as tumor-associated macrophages infiltrating the tumor stroma." (PMID 36090891, 2022). "In tumor biology, in general, abnormal high levels of lysyl oxidase paralogues expressed by tumor cells and/or associated stromal cells correlate well with poor outcomes in cancer." (PMID 35563478, 2022). "An in vivo experiment showed that tumor bearing mice displayed increased bone loss and formed focal osteolytic lesions over time before metastasizing, and these changes were lysyl oxidase (LOX)-dependent." (PMID 36059977, 2022). "The tumor suppression activity has been mostly associated with the LOX propeptide (LOX-PP) that is generated by the cleavage of the secreted pro-LOX by procollagen-C-proteinase." (PMID 33669630, 2021). "The complexities of correlating LOX family expression and tumour staging are typified in prostate cancer, where high LOX expression has been correlated with advanced tumour stage; however, low LOX expression was associated with decreased overall survival." (PMID 33513979, 2021).